LINC01139 (long independently transcribed non-coding RNA 1139)
Synonyms: LINK-A; TCONS_00000027; LINKA
Gene: Long non-coding RNA gene on chromosome 1 (238,476,542 to 238,486,060, reverse strand). Ensembl gene ENSG00000215808.
Diseases named in the same sentence as LINC01139 in open-access papers:
LINC01139 is named in the same sentence as 25 diseases in open-access papers, as found by Europe PMC text mining. Sharing a sentence is not in itself a finding about the gene and the disease. The quoted sentences say what the papers report.
breast cancer (23 papers, 2016 to 2026). A primary or metastatic malignant neoplasm involving the breast. "One example is the long intergenic non-coding RNA for kinase activation, Link-A (linc01139, (Δlog2 = 6.83, padj = 1.8 × 10−4), is highly expressed in breast cancer and has been shown to specifically interact with phosphatidylinositol 3,4,5-trisphosphate (PIP3) and Protein Kinase B (PKB/AKT)." (PMID 29535801, 2018).
tumor (20 papers, 2018 to 2026). "So far, several lipid‐associated lncRNAs, including small nucleolar RNA host gene 3 (SNHG3), small nucleolar RNA host gene 6 (SNHG6), and LINK‐A (formerly LINC01139), have been found to be involved in tumor progression." (PMID 40111100, 2025).
cancer (15 papers, 2018 to 2025). A tumor composed of atypical neoplastic, often pleomorphic cells that invade other tissues. "LINK-A (LINC01139) acts as an oncogene by downregulating cancer cell antigen presentation via suppression of PKA-mediated phosphorylation of the E3 ubiquitin ligase TRIM71." (PMID 37346034, 2023). "LINK-A, also LINC01139, is a lncRNA with increased expression in cancer cell lines." (PMID 34199840, 2021). "LINK-A, also recognized as LINC01139, has emerged as a key oncological lncRNA in cancer." (PMID 38645412, 2024).
LINC01139 also shares sentences with these, for which no sentence is quoted: triple-negative breast carcinoma (11 papers); osteosarcoma (4); ovarian carcinoma (4); glioma (3); Insulin resistance (3); lung carcinoma (3); non-small cell lung carcinoma (3); Obesity (3); mantle cell lymphoma (2); metabolic disorders (2); prostate carcinoma (2); bladder urothelial carcinoma (1); colorectal cancer (1); diabetic nephropathy (1); esophageal squamous cell carcinoma (1); liver cancer (1); metabolic syndrome (1); psoriasis (1); renal carcinoma (1); stomach adenocarcinoma (1); synovitis (1); thymoma (1).